MTOR (mechanistic target of rapamycin kinase)
Diseases named in the same sentence as MTOR in open-access papers (continued):
Sharing a sentence is not in itself a finding about the gene and the disease.
liver cancer (continued). "In support of our observations, studies have shown that PIK3CA is mutated in up to 30% of CRC as well as other tumors such as breast, ovarian, and liver cancer typically leading to activation of the PI3K/AKT/mTOR signaling pathway." (PMID 24943349, 2014). "The expression of mTOR and its downstream targets in Bel-7402 liver cancer cells and HL-7702 normal liver cells were examined by western blot." (PMID 23537100, 2013). "Here, we systematically examined the expression of mTOR and its downstream targets in liver cancer cells and normal liver cells, then investigated inhibitory effects of CCI-779 on mTOR signaling pathway and its role in regulating liver cancer cell growth." (PMID 23537100, 2013). "In this study, we analyzed the differences in mTOR expression between liver cancer and normal liver cells and treated Bel-7402 liver cancer cells with CCI-779 to show mTOR signaling has an important role in liver cancer cell growth regulation." (PMID 23537100, 2013). "Taken together, these data showed that CCI-779 can inhibit mTOR signaling and proliferation in Bel-7402 liver cancer cells in vitro." (PMID 23537100, 2013). "In conclusion, our results demonstrate the importance of the mTOR signaling pathway in regulating liver cancer cell proliferation." (PMID 23537100, 2013). "It offers a therapeutic intervention through inhibition of mTOR as a potential strategy for liver cancer." (PMID 23537100, 2013). "CCI-779 has inhibitory effects on Bel-7402 liver cancer cells by suppressing the activity of mTOR and its downstream components." (PMID 23537100, 2013). "In order to identify genetic alterations in the PI3K/AKT/mTOR signaling pathway in liver cancer, genomic DNA from 10 primary tumor samples of HCC patients were analysed by direct sequencing after PCR amplification." (PMID 23167739, 2012). "We demonstrated that treatment of liver cancer cells with mTOR inhibitor rapamycin and IKKβ inhibitor Bay11-7082 effectively blocked the HBx-induced cell proliferation and VEGF-A production." (PMID 22848663, 2012). "In conclusion, we demonstrate that HBx deregulates TSC1/mTOR signaling through IKKβ and renders liver cancer cells more sensitive to TNF-α stimulation in activating mTOR downstream S6K1 activity through IKKβ signaling." (PMID 22848663, 2012). "In liver cancer, GPER activation has been associated with anti-tumor effects via ERK signaling, whereas other studies have reported pro-tumorigenic roles through the PI3K/mTOR pathway." (PMID 40867252, 2025). "H2S can upregulate the expression of LC3-II and autophagy-related protein Atg5, two autophagy-related proteins, in HepG2 cells, while significantly inhibiting the expression of p-PI3K, p-Akt, and mammalian target of rapamycin (mTOR) proteins in liver cancer cells." (PMID 40442106, 2025). "4′-OH-TMF is a proliferative signal inhibitor at the level of mTOR, and the inhibitors of the PI3K/Akt/mTOR pathway have been extensively studied in cancer therapy, suggesting that citrulline and its metabolites may play an important role in anti-liver cancer." (PMID 39860170, 2025). "Furthermore, CD147 reprograms fatty acid metabolism in liver cancer cells through the Akt/mTOR/SREBP1c and P38/PPARα pathways, further underscoring the critical role of lipid metabolism in liver cancer." (PMID 41262444, 2025). "TSC2, a suppressor of mTOR, is inactivated in up to 20% of HBV-associated liver cancer." (PMID 39863613, 2025). "Similarly, ADAMTS9-AS2 inhibits the PI3K/Akt/mTOR pathway in liver cancer by upregulating ADAMTS9, promoting autophagy, and suppressing migration and invasion." (PMID 40350996, 2025). "Next, we sought to determine whether SESN3 was involved in the regulation of sorafenib resistance in mTOR-activated liver cancer cells." (PMID 39863613, 2025). "Therefore, exploring the mechanism of mTOR resistance to sorafenib is crucial for improving targeted therapy for liver cancer." (PMID 39863613, 2025).
liver cancer (continued). "Moreover, p-AKT and p-mTOR levels in hepatic cancer cells were lowered by the downregulation of SLC1A4 and deprivation of D-serine." (PMID 39949345, 2025). "A combination of pifithrin-μ and sorafenib may thus represent a novel therapeutic approach to overcome sorafenib resistance in mTOR-activated liver cancer." (PMID 39863613, 2025). "We found that mTOR-activated liver cancer cells were resistant to sorafenib-induced ferroptosis." (PMID 39863613, 2025). "FASN has been shown to promote colorectal cancer cell proliferation and metastasis through the AMPK/mTOR pathway, a mechanism that may also be relevant to liver cancer." (PMID 41262444, 2025). "Taken together, these findings suggest that PRDX6 may regulate the development of liver cancer partly through the PI3K/Akt/mTOR signaling pathways." (PMID 38544826, 2024). "Therefore, the IL-32γ overexpression induced autophagy by suppressing MET and mTOR pathways in liver cancer cell lines." (PMID 39519229, 2024). "Given the fact that the PI3K/AKT/mTOR pathway is a major signaling pathway that is abnormally activated in various cancer types, including liver cancer, wherein it promotes cell proliferation, growth, and angiogenesis that are vital for cancer metastasis and development." (PMID 37332348, 2023). "The Wnt/Notch and PI3K/Akt/mTOR signaling pathways are involved in liver cancer." (PMID 38371913, 2023). "Consequently, lignans block the mTOR pathway, resulting in an anti-colitis effect in immune cells, stress of the endoplasmic reticulum, death of liver cancer cells, and β-amyloid clearance in Alzheimer’s disease." (PMID 37534085, 2023). "Likewise, itraconazole increased intracellular ROS levels and inhibited AKT/mTOR/S6K signaling in liver cancer cells, leading to growth inhibition." (PMID 37351718, 2023). "In addition, YAP also promotes multi-drug resistance of liver cancer cells through the RAC1-Ros-MTOR pathway, thereby inhibiting autophagy-related cell death." (PMID 35173685, 2022). "However, EpCAM+ HCC1 and Huh7 cells as well as CD90+ HCC-derived SK-HEP1 cells rapidly developed resistance against the combined treatment with AKT and mTOR inhibitors in orthotopic liver cancer models in mice." (PMID 35454789, 2022). "Clinically, we uncovered a negative association between HPCAL1 and mTOR signaling and lipid metabolic enzymes in human liver cancers." (PMID 36438486, 2022). "In liver cancer cells such as HepG2 and MHCC97-L, berberine may also cause autophagic cell death through activation of Beclin-1 and inhibition of the mTOR-signaling pathway by downregulating Akt activity and upregulating P38 MAPK signaling." (PMID 36144625, 2022). "Finally, to elucidate the underlying mechanism of autophagy activation, we investigated the changes of some vital proteins in PI3K/Akt/mTOR signal pathway, an important pathway in the treatment of liver cancers and autophagy." (PMID 36353537, 2022). "Through mass spectrometry analysis and GO enrichment analysis, we found that the overexpression of NAP1L5 was highly related to the PI3K/AKT/MTOR signaling pathway and proved that NAP1L5 inhibited the progression of liver cancer through the PI3K/AKT/MTOR signaling pathway." (PMID 36374212, 2022). "Our study therefore has defined a key role of Rag-Rheb GTPase in mediating mTOR activation and drug resistance in senescence-like HepG2 cells, which could have important implications in developing second-line treatments for liver cancer patients." (PMID 36267578, 2022). "Moreover, combined with radiation, PKI-587, a dual PI3K/mTOR inhibitor, suppresses cell proliferation and tumor growth of liver cancer, accompanied by apoptosis." (PMID 36139919, 2022).
liver cancer (continued). "AKT/mTOR is overexpressed in liver cancer cells and induces upregulation of lipogenesis." (PMID 35624775, 2022). "Interestingly, HBV can dysregulate cellular signaling pathways, such as Wnt/FZD/β-catenin, PI3K/Akt/mTOR, and Ras/Raf/MAPK, associated with liver cancer development." (PMID 35280822, 2022). "They induce apoptosis of liver cancer cell lines by interfering with mTOR-dependent mechanisms." (PMID 36613653, 2022). "In addition, the expression of PIK3CA and mTOR also correlated with poor overall survival in liver cancer patients." (PMID 34716294, 2021). "Analyses of TCGA databases show the genetic alteration of PIK3CA and mTOR in liver cancer patients." (PMID 34716294, 2021). "Notably, they demonstrated that the accumulation of oleic acid (OA) and PA promoted liver cancer development by suppressing Pten, an inhibitor of Pi3k/Akt/mammalian target of rapamycin (mTOR) signaling." (PMID 33920670, 2021). "Double-inhibition of MET and MTOR efficiently enhanced liver cancer vaccination in mice." (PMID 32764535, 2020). "Finally, we found that RAB9A plays a procancer role in liver cancer cells by affecting the activation of the AKT/mTOR signaling pathway." (PMID 32420351, 2020). "In order to investigate the action mechanism underlying the procancer effect of RAB9A in human liver cancer cells, we proposed that the AKT/mTOR signaling pathway might be associated with the biological function of RAB9A." (PMID 32420351, 2020). "Finally, miR-99b expression was lower in TAMs of patients with liver cancer than that in adjacent tissues, while the expression of κB-Ras2 and mTOR was reversed." (PMID 32948650, 2020). "Similarly, the main mechanism of action of Azathioprine (AZA) in the treatment of liver cancer is through the activation of Ras/Raf/MEK/ERK/TSC2/mTOR-mediated autophagy to promote the senescence of HepG2." (PMID 31835352, 2019). "Moreover, Kaempferol can also activate autophagy of SK-HEP-1 (human hepatic cancer cells) by inhibiting the PI3K/AKT/mTOR pathway or activating the AMPK/mTOR pathway." (PMID 31835352, 2019). "Similarly, we have recently discovered that, as another important upstream pathway of autophagy, the AMPK/mTOR pathway also plays an increasingly important role in liver cancer." (PMID 31835352, 2019). "Therefore, another upstream pathway of autophagy, AMPK/mTOR, is also a new target for the treatment of liver cancer." (PMID 31835352, 2019). "Hence, the results suggested that Lanatoside C can act as an inhibitor for PI3K/AKT/mTOR pathway to induce apoptosis, cell cycle arrest, and inhibits autophagy in breast, lung, and liver cancer cells." (PMID 31783627, 2019). "For instance, it is stated that FXR could suppress the proliferation of liver cancer via the inhibition of mTOR/S6K signaling." (PMID 28402278, 2017). "Furthermore, simultaneous activation of AMPK, Akt and mTOR, has been observed in liver cancer cells following nutrient starvation." (PMID 27829024, 2016). "Moreover, an up-regulation of mTOR is frequently observed in cholangiocarcinoma, the second most common primary cancer of the liver." (PMID 27808117, 2016). "Our data showed the inhibitive effects of CCI-779 on mTOR signaling and liver cancer cell growth." (PMID 23537100, 2013). "Importantly, the tumor-promoting effects of CXCL3 were significantly suppressed by treatment with the mechanistic target of rapamycin (mTOR) inhibitor Torin 1, supporting the notion that targeting this pathway may provide therapeutic benefit in liver cancer." (PMID 41259383, 2025). "As tumor cells often exhibit increased metabolic antioxidant capacity through Warburg effect to promote proliferation, we speculated that activation of mTOR facilitates sorafenib resistance through increasing cellular antioxidant capacity of liver cancer cells." (PMID 39863613, 2025).
liver cancer (continued). "They proposed that mTOR inhibition might be used as a treatment for liver cancer." (PMID 36826066, 2023). "Therefore, this study took this as an entry point to speculate that TRMT6 may regulate the PI3K/AKT signaling pathway in which mTOR is located, thereby regulating the proliferation of liver cancer cells." (PMID 36707905, 2023). "Notably, we found that SVCT2-mediated uptake of VC can significantly inhibit mTOR pathway activation, which may also be one of the mechanisms by which VC preferentially eliminates liver cancer stem cells." (PMID 36787291, 2023). "Therefore, we speculate that, in this zebrafish liver cancer model, Sox9 may regulate hepatocyte dedifferentiation through the Wnt–mTOR signaling pathway." (PMID 35563098, 2022). "Thus, high SAMD1 expression could contribute to an augmentation of the mTOR signaling pathway in liver cancer cells, which may lead to enhanced cell growth." (PMID 35453756, 2022). "Furthermore, we analyzed the active ingredient-target-pathway network and uncovered that Fumaridine, Lastourvilline, N-feruloyl tyramine, and Cryptopine conclusively contributed to the development of liver cancer by affecting the MTOR, MAPK3, PIK3R1, and EGFR gene." (PMID 35745580, 2022). "Importantly, RAB9A activated the AKT/mTOR signaling pathway in human liver cancer cells." (PMID 32420351, 2020). "Moreover, mTOR pathway deregulation has been linked to liver cancer independent of the development of liver steatosis." (PMID 32070029, 2020). "Hence, MTOR inhibitors can improve liver cancer immunogenicity." (PMID 32764535, 2020). "Therefore, we investigated whether a combined treatment of MET and MTOR inhibitors can synergistically inhibit liver cancer cells in vitro." (PMID 32764535, 2020). "Therefore, PI3K/AKT/mTOR-mediated autophagy may be an important mechanism of liver cancer induced after HBV infection." (PMID 31835352, 2019). "However, the involvement of mTOR activation in liver cancer remains incompletely understood." (PMID 29515780, 2018). "Therefore, the drugs targeting PI3K/AKT/mTOR may be more effective than broad-spectrum chemotherapy such as 5-FU in prevention of liver cancer." (PMID 28680363, 2017). "However, according to the proteomics analysis, chitosan nanoparticle induced the liver cancer cell to secret several proteins which may active or enhance PI3K/AKT1/mTOR pathway." (PMID 24757677, 2014). "Thus, inhibition of mTOR is a potential therapeutic strategy for liver cancer." (PMID 23537100, 2013). "We found that SIRT2 can upregulate IGFBP1 expression and subsequently activate the PI3K/AKT/mTOR signalling pathway and that IGFBP1 is essential for the tumour-promoting function of SIRT2 in liver cancer." (PMID 42009830, 2026). "Another study highlighted its role in inhibiting the growth of hepatic cancer cells by blocking autophagic flux and inhibiting the PI3K/AKT/mTOR pathway." (PMID 40942095, 2025). "In a liver cancer study, MAF1 was reported to suppress AKT/mTOR signaling by activating PTEN transcription and inhibiting cell cycle progression." (PMID 39833662, 2025). "Metformin can also induce cell death through autophagy, as in vitro and in vivo models of liver cancer, the AMPK- mTOR axis is altered after metformin treatment." (PMID 40070568, 2025). "CircCOCH affects liver cancer progression by regulating miR-450a and activating the PI3K/mTOR pathway." (PMID 41229443, 2025). "XN has been shown to suppress the growth of various cancer cell lines, including breast, colon, prostate, and liver cancers, by modulating key signaling pathways such as NF-κB and PI3K/Akt/mTOR." (PMID 39942798, 2025). "According to the results from in vivo liver cancer mouse model, hepatic steatosis and the development of HCC were observed through the activation of the mTOR signal." (PMID 39349424, 2024).
liver cancer (continued). "To simulate liver cancer patients with both HBV infection and activation of PI3K/AKT/mTOR signaling pathway in mice, we disrupted Pten in the livers of HBV transgenic mice and investigated the role of GP73 in liver tumor development of HBV; Pten−/− mice." (PMID 38459588, 2024). "We administered a combination therapy of phosphoinositide 3-kinase/mammalian target of rapamycin (PI3K/mTOR) dual inhibitor BEZ235 and Lactobacillus rhamnosus HN001 to primary liver cancer model mice with cardiac allografts." (PMID 38564670, 2024). "Conversely, in liver cancer, CDDP-induced drug resistance correlates with lowered mTOR signaling with increased autophagy, as evidenced by elevated Beclin-1, increased LC3B-II, and reduced p62." (PMID 38560690, 2024). "Western blotting verified that the combination treatment of Cabozantinib and IL-32γ overexpression significantly decreased the mTOR-related proteins (p-mTOR, p-4E-BP1, and p-S6 kinase) and MET but increased p-ULK1 in the liver cancer cell lines." (PMID 39519229, 2024). "Further, the CucD-mediated downregulation of genes and proteins belonging to the PI3K/AKT/mTOR, MAPK, and JAK2/STAT3 cascades has been highlighted in liver cancer." (PMID 39770403, 2024). "The combination of 6-shogaol and 5-FU inhibit AKT/mTOR/MRP1 signaling pathway and induce liver cancer cell apoptosis by decreasing the expression of AKT, mTOR, MRP1 and cyclin-related proteins." (PMID 36865794, 2023). "All liver cancers reported dysfunction in the WNT/β-catenin and P13K/AKT/mTOR pathways as well as changes in FGFR." (PMID 36768732, 2023). "The current study found that the PI3K/AKT/mTOR and the caspase-3/Bax/Bcl-2 signaling pathways involved B. coagulans MZY531 mediated inhibition of liver cancer progression." (PMID 37705007, 2023). "The dysregulation of the PI3K/AKT/mTOR signaling pathway is common in HCC and is, therefore, a topic of further research and the concern of developing a novel target for liver cancer therapy." (PMID 36768977, 2023). "This review reports that the WNT/β-catenin and P13K/AKT/mTOR pathways were reported in literature for HB, CCA and HCC liver cancers and FGFR changes over all liver cancers." (PMID 36768732, 2023). "As a key upstream kinase that activates AMPK, LKB1 was downregulated in liver cancer, preventing AMPK activation and upregulating mTOR expression." (PMID 36937390, 2023). "In liver cancer, FXR overexpression suppresses proliferation of human liver cancer cells via the inhibition of the mTOR/S6K signaling pathway." (PMID 35563650, 2022). "Comparing these findings with those provided by enrichment analysis four genes in particular, EGFR, MAPK3, MTOR, and PIK3R1, were identified as the main anti-liver cancer targets of F. indica and were chosen for molecular docking experiments." (PMID 35745580, 2022). "This PKI-587/radiation combined treatment inhibits PI3K/AKT/mTOR and homologous recombination (HR) repair-related kinases such as the ATM and the ATM and Rad3-related (ATR) in liver cancer cells." (PMID 36139919, 2022). "Expression levels of mTOR and its downstream P70S6K in the PI3K-AKT-mTOR signaling pathway are usually upregulated in liver cancer compared to paracancerous and normal liver tissues." (PMID 35647006, 2022). "The inhibition of GSK-3β activity inhibited liver cancer progression, and this anticancer effect was mainly achieved through the AMPK/mTOR signaling pathway." (PMID 35722140, 2022). "Peruvoside, a Cascabela thevetia-derived cardiac glycoside, induces antiproliferation and DNA damage and inhibits autophagy in breast, lung, and liver cancer cells, accompanied by PI3K/AKT/mTOR." (PMID 36139919, 2022).